RNU6-1088P (RNA, U6 small nuclear 1088, pseudogene)
Gene: Small nuclear RNA gene on chromosome 12 (120,313,238 to 120,313,341, reverse strand). Ensembl gene ENSG00000252659.
Homologues: Orthologues: chimpanzee U6 (99% identical), macaque U6 (88% identical), rabbit U6 (88% identical), guinea pig U6 (81% identical), pig U6 (76% identical), guinea pig U6 (74% identical), mouse Gm55761 (71% identical). Paralogues in human: RNU6-66P (89% identical), RNU6-1060P (88% identical), RNU6-1175P (88% identical), RNU6-189P (88% identical), RNU6-19P (88% identical), RNU6-23P (88% identical), RNU6-242P (88% identical), RNU6-24P (88% identical), RNU6-266P (88% identical), RNU6-767P (88% identical), RNU6-949P (88% identical), RNU6-116P (87% identical), and 1284 more.